LIPT1 (lipoyltransferase 1)
Diseases named in the same sentence as LIPT1 in open-access papers (continued):
Sharing a sentence is not in itself a finding about the gene and the disease.
mesothelioma (1 paper, 2022). A usually malignant and aggressive neoplasm of the mesothelium which is often associated with exposure to asbestos. "Similarly, cuproptosis-associated genes including LIAS, LIPT1, PDHB, GLS, and CDKN2A had significant overall survival in Mesothelioma (MESO) (p < 0.05)." (PMID 36105090, 2022).
ovarian serous cystadenocarcinoma (1 paper, 2022). A malignant serous cystic epithelial neoplasm arising from the ovary. "We found the down-regulated LIPT1 in adrenocortical carcinoma (ACC), ovarian serous cystadenocarcinoma (OV), testicular germ cell tumors (TGCT) and uterine carcinosarcoma (UCS)." (PMID 36330439, 2022).
retinoblastoma (1 paper, 2022). A malignant tumor that originates in the nuclear layer of the retina. "In retinoblastoma (RB), the expression of LIPT1 was negatively associated with cell cycle, DNA repair response, EMT and invasion." (PMID 36330439, 2022).
septic shock (1 paper, 2024). Shock caused by infection; frequently caused by gram negative bacteria, although some cases have been caused by other bacteria, viruses, fungi, and protozoa; characterized by fever, chills, tachycardia, tachypnea, and hypotension. "In the present study, we found that LIAS and LIPT1 exhibited a positive correlation with CD8+ T cells, suggesting that LIAS and LIPT1 may contribute to improving immune status in septic shock patients by elevating the number of CD8+ T cells." (PMID 39652607, 2024).
synovitis (1 paper, 2023). Inflammation of a synovial membrane. "In our research, the downregulation of DBT and DLST, together with the upregulation of FDX1 and LIPT1, may indicate the potential role of cuproptosis in OA synovitis." (PMID 36671512, 2023).
ulcerative colitis (1 paper, 2025). An inflammatory bowel disease involving the mucosal surface of the large intestine and rectum. "In ulcerative colitis, LIPT1 and PDHA1-related cuproptosis disrupts epithelial cells, advancing the disease." (PMID 40655146, 2025). "A study conducted on ulcerative colitis (UC) revealed that both LIPT1 and PDHA1 are key genes to promote cuproptosis, which can induce the abnormal death of intestinal epithelial cells and lead to the occurrence of UC." (PMID 40655146, 2025).
uveal melanoma (1 paper, 2022). A melanoma derived from melanocytes of the uveal tract. "LIPT1 expression in uveal melanoma (UM) had a negative relationship with almost all tumor biological behaviors, such as cell death, DNA damage response, invasion and metastasis." (PMID 36330439, 2022).
tumor (49 papers, 2022 to 2025). "Demonstrated to function as a tumor suppressor, LIPT1 presented potential as a diagnostic marker for NSCLC." (PMID 38041690, 2024). "Following 10-Gy IR, the tumor growth delay was significantly greater in LIPT1−/− tumors compared to the control tumors." (PMID 40073141, 2025). "Loss of LIPT1 inhibits the TCA cycle, forcing tumor cells to augment glycolysis to acquire energy essential for growth." (PMID 40253387, 2025). "Loss of LIPT1 disrupts the TCA cycle, potentially forcing tumor cells to rely on glycolysis, while making them less sensitive to copper-dependent cell death." (PMID 40253387, 2025). "Surprisingly, IDH2R140Q mutation changed the expression patterns of cupropotosis-associated genes, including FDX1, LIAS, LIPT1, DLD, DLAT, and PDHA1, which indicated that the sensitivity of tumor cells to cuproptosis depends on the types of genetic mutations." (PMID 40384935, 2025). "In essence, LIPT1 emerges as a prospective tumor suppressor and holds promise as a prognostic marker in NSCLC." (PMID 38041690, 2024). "The high-expression LIPT1 group manifested a diminished tumor immune dysfunction and escape (TIDE) score, while a positive correlation was noted between TMB and LIPT1 expression." (PMID 38041690, 2024). "Our study identified LIPT1 as a valuable prognostic biomarker in NSCLC as it elucidates its tumor-inhibitory role through the modulation of ATOX1." (PMID 38041690, 2024). "The findings from the western blot were also consistent, demonstrating reduced LIPT1 protein levels in these tumor cell lines." (PMID 38041690, 2024). "Differential expression between normal tissues and BRCA tissues at each tumor stage was found in almost all cuproptosis-associated genes; however, only LIPT1, DLAT, PDHA1, and CDKN2A were differentially expressed among tumor stages." (PMID 39432636, 2024). "The methylation levels of LIAS, PDHB, and LIPT1 in the PDAC tumor tissues were significantly different from those in the normal tissues (FDR < 0.05)." (PMID 36826087, 2023). "Difference analyses showed that 7 of 10 CRGs were dys-regulated in tumor samples compared with those in normal samples, among which LIPT1, PDHA1, GLS and CDKN2A were up-regulated, and FDX1, DLD and MTF1 were down-regulated." (PMID 37333810, 2023). "The genes LIPT1, PDHA1, and PDHB are responsible for encoding the lipoic acid pathway, which has been found to have significant implications in tumor progression." (PMID 38114959, 2023). "We divided the tumor patients into two subgroups according to the expression of LIPT1, namely, the LIPT1-high and LIPT1-low groups." (PMID 35837286, 2022). "The expression of LIPT1 was significantly decreased in several tumor tissues, including BRCA, CESC, KIRC, KIRP, THCA, UCEC, and KICH." (PMID 36330439, 2022). "At the same time, there were significant differences in LIPT1 methylation levels between tumor tissues and normal tissues." (PMID 36330439, 2022). "The scatter plot showed that LIPT1 levels were higher in LIHC tumor samples compared with normal samples." (PMID 36195876, 2022). "LIPT1, encoding fatty acyltransferase 1, is a crucial regulator of lipoic acid (LA) transport, while LA significantly participates in the TCA cycle, as well as mitochondrial metabolism in tumor cells." (PMID 40367233, 2025). "Moreover, PNPLA2 showed an overexpression in normal tissues than that in tumor tissues, whereas all the other genes, except LIPT1, were up-regulated in the tumor tissues." (PMID 40568577, 2025). "Additionally, we also investigated the expression of cuproptosis‐related genes between tumour and normal samples in the TCGA ESCA cohort and found that the expression of DLAT, GLS and LIPT1 was increased in tumour samples (p < 0.05)." (PMID 38429907, 2024). "This points to the potential tumor suppressor role of LIPT1 in NSCLC." (PMID 38041690, 2024). "We compared the methylation values of LIPT1 between normal and tumor tissues." (PMID 36330439, 2022).
tumor (continued). "Since the further GSVA of LIPT1 upregulated genes revealed the enrichment in some metabolism and cell death-related pathways, upregulated LIPT1 might inhibit tumor cell proliferation by inducing other forms of RCD." (PMID 35837286, 2022). "Previous studies have shown that LIPT1 is positively correlated with tumor progression." (PMID 36497253, 2022). "Meanwhile, the potential implications of LIPT1 in anti-tumor immune response were also explored." (PMID 36330439, 2022). "Additionally, the results indicated that tumor purity was only significantly correlated with LIPT1 (cor = 0.176, p = 5.84 × 10−3), NCOA6 (cor = 0.302, p = 1.43 × 10−6) and PRPF4B (cor = 0.188, p = 3.06 × 10−3), respectively." (PMID 36552841, 2022). "There is little evidence that LIPT1 is associated with tumor occurrence and development." (PMID 37124062, 2023). "Therefore, upregulated LIPT1 might improve the response to immunotherapy by inhibiting Treg infiltration in the tumor microenvironment." (PMID 35837286, 2022). "However, the detailed roles of LIPT1 in different tumor types remains elusive." (PMID 36330439, 2022). "In the GPL570 dataset, upregulation of LIPT1, FDX1, LIAS, DLAT, DLD, and PDHB was noted in tumor samples, while MTF1 was downregulated." (PMID 40410601, 2025). "Inhibiting lipoylation, either through genetic LIPT1 knockout or a lipoylation inhibitor (CPI-613), enhanced tumor control by radiation." (PMID 40073141, 2025). "Specifically, genes such as LIPT1, ATP7A, LIAS, DBT, and PDHB were found to be significantly downregulated in the tumor tissue." (PMID 38898987, 2024). "It has been reported that the expression of CDKN2A, GLS and LIPT1 is positively correlated with the abundance of CD8+T cells and neutrophils and CDKN2A expression positively correlated with the degree of tumor infiltration, which was in line with our study." (PMID 36843949, 2023). "The PDAC patients with higher expression levels of PDHA1, LIPT1, LIAS, and DLD, or lower expression levels of DLAT, in their tumor tissues had a better prognosis than their counterparts (p < 0.05)." (PMID 36826087, 2023). "Among them, the expression levels of CDKN2A, GLS and LIPT1 were significantly upregulated whereas the expression levels of DLAT, DLD, FDX1, MTF1 was significantly downregulated in tumor samples." (PMID 37072493, 2023). "In tumor tissues, the abundance of CDKN2A and MTF1 were higher, as well as the levels of DLD, FDX1, GLS, LIPT1 and PDHB were down-regulated." (PMID 37662947, 2023). "Other genes such as LIPT1, FDX1, and SLC31A1 also play important roles in tumor growth and patient prognosis." (PMID 37239150, 2023). "Therefore, LIPT1 might be a potential prognosis biomarker and immune target for tumor patients." (PMID 36330439, 2022). "The results showed that, in tumor samples, ATP7B, PDHA1, and SLC31A1 were significantly upregulated compared with normal tissues, whereas ATP7A, DLST, GCSH, LIAS, and LIPT1 were significantly downregulated." (PMID 36567939, 2022). "Among them, 7 genes (DLAT, DLD, GCSH, LIAS, LIPT1, PDHA1, and PDHB) were upmodulated, whereas 3 genes (ATP7B, FDX1, and SLC31A1) were downmodulated in the tumor group in contrast with the normal group (p < 0.05)." (PMID 36046242, 2022). "CDKN2A, GLS, LIPT1, and PDHA1 were up-regulated in tumor samples, and FDX1, DLD, MTF1 were down-regulated in tumor samples." (PMID 36176287, 2022). "Additionally, increased mRNA level of CDKN2A, DLAT, GLS, LIPT1, and MTF1 in tumor were observed compared to normal group." (PMID 36703728, 2022). "Moreover, further analysis was made to investigate the mRNA expression level of CRGs between normal and CRC samples, and we found that the expressions of FDX1, DLD, DLAT, PDHB, and MTF1 were significantly decreased, whereas LIPT1, GLS, and CDKN2A were significantly upregulated in tumor samples." (PMID 37006250, 2023).
tumor (continued). "In our study, we suppose that LIPT1 may act as a tumor suppressor in LUAD by regulating other pathways rather than influencing the immune microenvironment." (PMID 36313439, 2022). "We found that FDX1, LIPT1, DLAT, PDHA1, PDHB, DLST, and ATP7A were significantly differentially expressed in tumor and nontumor tissues, with the standard of p < 0.05." (PMID 36975441, 2023).
cancer (29 papers, 2020 to 2025). A tumor composed of atypical neoplastic, often pleomorphic cells that invade other tissues. "Using cancer cell lines deficient in LIPT1 or treated with a lipoylation inhibitor, we confirmed a radiosensitization effect by lipoylation inhibition." (PMID 40073141, 2025). "The association between LIPT1 expression and immune checkpoints in cancer patients still needs to be explored in more preclinical and clinical trials." (PMID 36330439, 2022). "In this study, by using multiple bioinformatics methods, we explored the underlying molecular mechanisms of LIPT1 in the pathogenesis and clinical prognosis of multiple human cancers." (PMID 36330439, 2022). "To explore the gene mutation of LIPT1 in various cancers, we analyzed its mutation status through cBioPortal platform based on TCGA data." (PMID 36330439, 2022). "In this study, we found that LIPT1 expression was strongly correlated with the infiltration of immune cells, including B cell, cancer-associated fibroblast and CD8+ T cells." (PMID 36330439, 2022). "The expression of LIPT1 is associated with the infiltration of many immune cells in various cancers." (PMID 36276092, 2022). "Pan-cancer analysis suggested the high LIPT1 amplification in BLCA (>2%) and high mutation in UECE (>3%)." (PMID 36330439, 2022). "Recent analyses based on cuproptosis-related genes have linked LIPT1 with cancer outcomes." (PMID 40073141, 2025). "Furthermore, LIPT1-deficient panceratic cancer cells invading the Matrigel barrier were remarkably decreased as compared to control cells." (PMID 40367233, 2025). "Moreover, LIPT1 expression is positively correlated with PD-L1 expression and negatively associated with Treg cell infiltration, suggesting that LIPT1 can guide immunotherapy in patients with cancer." (PMID 37767404, 2023). "The results suggested that LIPT1 may be a novel potential prognostic and immune-associated biomarker for cancer patients." (PMID 36330439, 2022). "We also explored the mutational status and methylation levels of LIPT1 in human cancers." (PMID 36330439, 2022). "Our exploratory findings demonstrated that LIPT1 genetic alterations, including mutation and deep deletion, could be observed in a variety of cancers." (PMID 36330439, 2022). "Genes such as FDX1, CAT, CDKN2A, DLAT, LIPT1, and COMMD1, which are associated with cuproptosis, are crucial for the growth, advancement, and spread of various cancers." (PMID 40109870, 2025). "Evidence has shown that cuproptosis-related genes (e.g. PDXK, FDX1 and LIPT1) can affect the progression of human cancers." (PMID 39652607, 2024). "CNV displayed a high frequency in CDRs in most cancer types, among which the expression level of LIPT1 displayed a positive correlation with CNV events, and other CDRs exerted heterogeneous relationships according to cancer types." (PMID 36766692, 2023). "The result from single cell sequencing reflected the important roles of LIPT1 in the regulation of several biological behaviors of cancer cells, such as DNA damage response and cell apoptosis." (PMID 36330439, 2022). "In conclusion, using comprehensive bioinformatics analysis techniques, we explored the expression levels, clinical prognosis, methylation values, genetic alterations, and immunomodulatory effects of LIPT1 in pan-cancer." (PMID 36330439, 2022). "Here, we comprehensively analyzed the functional characteristics of LIPT1 in human cancers and its roles in immune response." (PMID 36330439, 2022). "The CCK8 assay showed that LIPT1 depletion inhibited cancer cell proliferation in HepG2 and Hep3B cells." (PMID 36195876, 2022). "Hypermethylated PDHB, LIPT1, LIAS and GLS were mainly associated with poor prognosis in cancer, whereas hypomethylated FDX1 was dominantly related to poor prognosis of LGG and ccRCC." (PMID 36581992, 2022).
cancer (continued). "Several algorithms, such as TIMER, EPIC, QUANTISEQ, XCELL, MCPCOUNTER, CIBERSORT, CIBERSORT-ABS, and TIDE, were applied to explore the correlation between LIPT1 expression and the infiltration of different immune cells in pan-cancer." (PMID 36330439, 2022). "The CCK8 assay showed that LIPT1 depletion inhibited cancer cell proliferation in HepG2 and Hep3B cells (P < 0.05)." (PMID 36195876, 2022). "Whereas LIPT1 expression was negatively correlated with regular T cell and macrophage M0 cell in most cancers." (PMID 36518756, 2022). "The results showed that cuproptosis-related genes such as PDHB, PDHA1, DLAT, DLD, LIPT1 were significantly positively correlated with FDX1 in pan-cancer." (PMID 35991547, 2022). "The findings presented here shed light on the potential role of the LIPT1 gene in cancer onset and progression." (PMID 36276933, 2022). "Gene enrichment analysis indicated that abnormally expressed LIPT1 was significantly associated with immune cells infiltration, such as B cells, CD8+ T cells and cancer-associated fibroblast cells." (PMID 36330439, 2022). "Further, we analyzed the expression of LIPT14 in pan-cancer, and we found that LIPT1 and IL-15 had a strong and significant positive correlation in SKCM and READ, and a general level of positive correlation in LUAD, ESCA, PCPG (p less than 0.05), but not with UCS, COAD." (PMID 36467072, 2022). "Taken together, our research could provide a comprehensive overview about the significances of LIPT1 in human pan-cancer progression, prognosis and immune." (PMID 36330439, 2022). "In addition, abnormally expressed LIPT1 was significantly associated with immune cells infiltration, such as B cells, CD8+ T cells, and cancer associated fibroblast cells." (PMID 36330439, 2022). "In addition, IL-15 is positively correlated with ferroptosis/cuproptosis-related genes (ACSL4 and LIPT1) in pan-cancer." (PMID 36467072, 2022). "We further explored the correlation between the expression of LIPT1 and eight immune checkpoints (PD-L1, CTLA4, HAVCR2, LAG3, PDCD1, PDCD1LG2, SIGLEC15, and TIGIT), and found that LIPT1 levels were correlated with the expressions of these immune checkpoints, especially PD-L1, in most cancer types." (PMID 35837286, 2022). "And single cell sequencing and gene enrichment indicated that LIPT1-correlated gene might regulate several cancer biological functions, such as DNA damage response and cell death." (PMID 36330439, 2022). "Initially, we examined LIPT1 expression levels in pan-cancer by TIMER2.0." (PMID 36330439, 2022). "The prognostic value of LIPT1 in these cancers was subsequently evaluated." (PMID 35837286, 2022). "Finally, a pan-cancer analysis indicated that LIPT1 was differentially expressed in diverse cancers as compared to normal tissues and correlated with the expression of multiple immune checkpoints, especially PD-L1." (PMID 35837286, 2022). "However, the biological significances of LIPT1 in the pan-cancer are unclear." (PMID 36330439, 2022). "In addition, we acquired the top 100 LIPT1 co-expressed genes in pan-cancer from GEPIA2.0." (PMID 36330439, 2022). "Meanwhile, a negative correlation between the infiltration of cancer-associated fibroblasts and LIPT1 expression could be found in PRAD and TGCT." (PMID 36330439, 2022). "Machine learning models based on seven LM-related genes (CHEK2, LIPT1, TUFM, NDUFA10, AGK, PNPLA2, and GFM1) accurately predicted immunotherapy outcomes for multiple cancer types, including LUSC, and outperformed other currently known biomarkers." (PMID 40568577, 2025). "In this pan-cancer analysis, we systematically profiled the expression and prognostic value of eight well-characterized cuproptosis-related genes—FDX1, LIAS, LIPT1, DLD, DLAT, PDHA1, PDHB, and SLC31A1—across 34 cancer types." (PMID 40601654, 2025). "In contrast, eight regulators (PDHA1, ATP7A, LIPT1, LIPT2, GLS, ATP7B, GCSH, and CDKN2A) were upregulated in cancer tissues." (PMID 36672336, 2023).
cancer (continued). "The three genes (GCSH, LIPT1, CDKN2A) that we used to construct cuproptosis-related prognostic models played important roles in the progression of various types of cancer." (PMID 36195876, 2022). "However, the role of the LIPT1 gene in cancer onset and progression remains unknown." (PMID 36276933, 2022). "Germline mutations in LIAS, LIPT2 and LIPT1 result in impaired PDHc and OGDHc activity, but ABHD11 loss did not significantly alter DLAT lipoylation in several cancer lines." (PMID 32792488, 2020). "LA is a component of the PDH complex, and lipoyltransferase 1 (LIPT1), a recently identified cuproptosis-related gene, transfers LA from glycine cleavage system protein H to the E2 subunit of lipoylated substrates, thereby influencing PDH activity, as observed in cancer and metabolic studies." (PMID 40642746, 2025).
metabolic disorders (3 papers, 2022 to 2025). "Recently, the DeBerardinis's group investigated metabolic disorders due to defects in the gene encoding lipoyltransferase-1 (LIPT1), which catalyzes the transfer of lipoic acid to the E2 subunits of 2-keto dehydrogenases, PDH and α-KGDH." (PMID 35178152, 2022).